BRAF (B-Raf proto-oncogene, serine/threonine kinase)
Diseases named in the same sentence as BRAF in open-access papers (continued):
Sharing a sentence is not in itself a finding about the gene and the disease.
thyroid cancer (continued). "Mutations in protein BRAF can affect the expression of noncellular components of tumor ECM (extracellular matrix) via MAPK signaling pathway to upregulate thyroid cancer microenvironmental regulator TSP1, thus changing the microenvironment in PTC." (PMID 31126066, 2019). "BRAF V600E promoter mutation, in combination with TERT or RAS mutation, was recognized as clinically important diagnostic and prognostic genetic markers for thyroid cancer." (PMID 31300059, 2019). "Of note, PLX4720, by downregulating the expression of genes involved in tumor progression, reduced cell proliferation, migration and invasiveness of 8505c, which harbor the BRAF mutation, but not in TPC-1 (wild-type for BRAF) thyroid cancer cells." (PMID 31762942, 2019). "It has been recently found that using dabrafenib, the BRAF V600E inhibitor could partially induce radioiodine uptake in RAI-refractory thyroid cancer in patients, suggesting that the therapeutic effectiveness of RAI treatment using single agents was limited." (PMID 30337961, 2018). "Interestingly, BRAF V600E was widely found to be associated with TERT promoter mutations in human cancers, particularly thyroid cancer and melanoma." (PMID 29422527, 2018). "We therefore suggested that targeting BRAF/MAPK or MEK/ERK pathway could be clinically effective in restoring RAI avidity in RAI-refractory thyroid cancer." (PMID 30337961, 2018). "Therefore, we examined the efficacy of the combination therapy across a panel of thyroid cancer cell lines representing common oncogenic drivers (BRAF, RAS, and PIK3CA)." (PMID 29487290, 2018). "An association between the TERT –245T>C polymorphism and BRAF mutation was investigated, but not found, in a study on differentiated thyroid cancer, showing that BRAF mutation was not correlated to TERT –245T>C polymorphism as an additional prognostic factor." (PMID 29464027, 2018). "This was not necessarily expected as we hypothesized they are more reliant on MAPK signaling; however, similar growth responses have been observed in BRAF-mutant thyroid cancer cell lines treated with rapamycin." (PMID 29262541, 2017). "In summary, the present study identifies the WIPF1 gene as having novel oncogenic functions and playing an important role in the invasiveness and aggressiveness of thyroid cancer when aberrantly up-regulated by the BRAF V600E/MAPK pathway through its promoter demethylation." (PMID 27863429, 2017). "However, unlike in metastatic melanoma, the treatment effects of vemurafenib in BRAF (V600E) mutant thyroid cancer are often insignificant." (PMID 27880942, 2017). "Indeed, the pan-HER TKi lapatinib prevents ERK rebound and sensitizes BRAF-mutant thyroid cancer cells to RAF or MAPK kinase inhibitors." (PMID 29033690, 2017). "The same process could take place during inhibition of mutant BRAF in thyroid cancer, by drug treatment, and the patient may ultimately escape the effects of therapy." (PMID 28117292, 2017). "This pathway is commonly activated by the BRAF V600E in human cancers, including thyroid cancer." (PMID 27863429, 2017). "Clearly, BRAF V600E plays an important role in the tumorigenesis and aggressiveness of thyroid cancer, yet the underlying molecular mechanisms are not fully understood." (PMID 27863429, 2017). "The fundamental causative mechanism for this differential drug response in different types of BRAF (V600E) mutant thyroid cancer is unknown and is beyond the scope of this study but further investigation is warranted." (PMID 27880942, 2017). "Following this, a clinically relevant antitumor activity of these BRAF inhibitors could also be demonstrated in patients with advanced V600E-mutant non–small-cell lung cancer, thyroid cancer, and hairy cell leukemia." (PMID 29312620, 2017). "BRAF V600E plays a key role in the tumorigenesis and pathogenesis of thyroid cancer." (PMID 27863429, 2017).
thyroid cancer (continued). "This provides a novel mechanism underlying the invasiveness and aggressiveness of PTC promoted by the BRAF V600E and a potential novel therapeutic target for BRAF V600E-harboring thyroid cancer, particularly promising in cases where BRAF V600E inhibitors fail due to drug resistance." (PMID 27863429, 2017). "A partial and transient cytostatic response to PLX4032 was observed in thyroid carcinoma cell lines bearing the BRAF V600E mutation, with lack of full inhibition of ERK pathway." (PMID 29033690, 2017). "This study evaluated the hypothesis that feedback activation of EGFR signaling counteracts the cytostatic activity of vemurafenib (PLX4032) in BRAF V600E thyroid carcinoma cells." (PMID 29033690, 2017). "The possible effects of drinking and BRAF mutations on colon cancer risk have been examined, although, no related studies of drinking and thyroid cancer risk have been performed." (PMID 26985827, 2016). "At variance with these results, metformin did not affect the TNF-α-stimulated secretion of CXCL8 in thyroid cancer cell lines harboring the RET/PTC rearrangement or the BRAF V600e mutation (TPC-1 and BCPAP cells, resp)." (PMID 27555670, 2016). "We investigated whether the Wnt/ß-catenin pathway was active in the earliest steps of thyroid tumorigenesis driven by RAS and BRAF, the two main oncogenes in thyroid cancer." (PMID 27384483, 2016). "Therefore, efforts have been directed towards use of selective BRAF V600E inhibitors in thyroid cancers as systemic therapies." (PMID 27127178, 2016). "Because PTC is the most common thyroid carcinoma, we included BRAF and RET/PTC in our research." (PMID 27654865, 2016). "Although the BRAF mutation alone is not sensitive enough to detect majority of thyroid cancers, a test to detect other molecular abnormalities in combination with BRAF mutations were found to increase the sensitivity." (PMID 29061943, 2015). "Among the BRAFV600E-specific differentially expressed 18 genes, there are two involved in the calcification of epithelial cells: SLC34A2 and ITPR3, with the latter not previously related to BRAF mutation or to thyroid cancer." (PMID 26625260, 2015). "Indeed, in thyroid cancer, BRAF-mediated miR-17-92 up-regulation leads to a reduction of Smad4 and Tgfbr2 proteins and a loss of responsiveness to TGFβ1." (PMID 26442266, 2015). "Here we present a detailed analysis of kinase inhibition, effects on the cell cycle and apoptosis induction by the BRAF- and multikinase inhibitor, sorafenib, in thyroid carcinoma cell lines of various histological subtypes with and without activating BRAFV600E mutations." (PMID 25879531, 2015). "Whereas a BRAF mutation represents a valuable target for molecular therapy in advanced solid tumors such like PTCs, valuable molecular targets in thyroid carcinomas bearing no BRAF mutation are less known." (PMID 25923053, 2015). "Thus, the finding of histone deacetylation of NIS promoter by BRAF V600E in this study provides an important epigenetic mechanism for the downregulation of NIS gene in BRAF V600E-harboring thyroid cancer." (PMID 24243688, 2014). "Both previous and this studies demonstrated an upregulation of global histone acetylation by BRAF V600E, which initially seemed to be puzzlingly against our proposed mechanism in which BRAF V600E-mediated downregulation of NIS gene involves deacetylation of histone in thyroid cancer." (PMID 24243688, 2014). "It has been recently hypothesized that BRAF V600E/MAPK pathway might downregulate histone acetylation as a mechanism involving aberrant silencing of thyroid iodide-handling genes in thyroid cancer." (PMID 24243688, 2014). "We evaluated the presence or absence of BRAF gene mutation in the four thyroid cancer cell lines used in the study." (PMID 24727741, 2014).
thyroid cancer (continued). "In this study, we have demonstrated that SPP86 selectively inhibits this activity in a thyroid cancer cell line expressing RET/PTC1 but not in others with activating mutations in BRAF (V600E) or Ras (G13R) which lie downstream of RET." (PMID 25409876, 2014). "Interestingly, AMPK suppressed the phosphorylation of ERK (extracellular-signal-regulated kinase) and p70S6K (mTOR target), in BRAF V600E mutant thyroid cancer cells, but rather increased their phosphorylation in wild-type cells." (PMID 27919039, 2014). "BRAF V600E-promoted loss of expression of NIS and other thyroid genes and hence the development of radioiodine refractoriness currently represent a major therapeutic obstacle for thyroid cancer patients." (PMID 24243688, 2014). "Mutations in BRAF and RAS are commonly found in well-differentiated thyroid cancers, but they are also found in poorly differentiated and undifferentiated thyroid cancer types, so it would be reasonable to suggest that these mutations represent an early event in the progression of thyroid cancers." (PMID 25276134, 2014). "The dependence of these papillary thyroid cancer cells on signaling through the MAPK pathway and the resulting profound anti-cancer effects by BRAF inhibition can be characterized as “oncogene addiction” and validate targeting the BRAFV600E mutated protein in thyroid cancer cells." (PMID 24673746, 2014). "Third, genetic markers were not considered in the present study; however, BRAF, the most frequent mutation in thyroid cancer, seems to be less important in follicular neoplasms." (PMID 25506397, 2014). "Although clinical studies of BRAF inhibitors in advanced non RAI-responsive differentiated thyroid carcinomas have shown encouraging results with frequent early responses, in a relevant fraction of patients this effect was of limited duration, with frequent relapse or no response." (PMID 24267151, 2013). "One of the limitations of our study is the non-availability of BRAF(V600E) mutation data in our cohort of thyroid cancer patients." (PMID 22911723, 2012). "DNA from the tumor and adjacent benign thyroid tissue was tested by PCR/direct sequencing of genomic DNA for genetic abnormalities that have been described in thyroid cancer originating in the neck, including a portion of BRAF exon 15 and codons 12, 13, 31, 60 and 61 of K-H- and N-RAS." (PMID 22682753, 2012). "PTEN is downregulated in ~37% of well-differentiated thyroid carcinomas and downregulated or lost in >50% of highly malignant thyroid cancers; point mutations or copy number changes in PIK3CA are found in ~23% of anaplastic thyroid cancers where they can coexist with either RAS or BRAF mutations." (PMID 22927847, 2012). "A limitation of the current study is the non-availability of BRAF (V600E) mutation data in our cohort of thyroid cancer patients." (PMID 23049733, 2012). "Constitutive activation of RET, RAS, and BRAF which are principle initiators of thyroid cancer." (PMID 22654559, 2011). "Based on evidence that BRAF is involved in the development of papillary carcinoma and in the progression to anaplastic cancer, BRAF is an attractive target in thyroid cancer, especially anaplastic and aggressive papillary subtypes where there is an urgent need for treatment." (PMID 22654559, 2011). "In thyroid cancer cells the target molecules, implicated on the cellular effects, mediated by inhibition of BRAF are not well established." (PMID 19878585, 2009). "Our results support the hypothesis that thyroid cancer cells with activated BRAF are more dependent on the BRAF-ERK pathway for proliferation than those with RAS or RET/PTC1 activation." (PMID 19878585, 2009).
thyroid cancer (continued). "In thyroid carcinomas the molecules and pathways associated to the effect of BRAF inhibition in cellular proliferation and survival are not fully understood." (PMID 19878585, 2009). "Our findings contrast with a recent report showing a positive correlation between a KRAS or BRAF mutation and clinical aggressiveness in colorectal, non-small-cell lung, and thyroid cancers." (PMID 19018267, 2008). "This potential may not be limited to just PTCs with BRAF-activating mutations because BRAF and the entire RAF kinase family are activated by other oncogenes involved in thyroid cancer development, in both PTC and follicular carcinomas." (PMID 17179987, 2007). "Several studies have demonstrated the ability of this agent to inhibit proliferation of poorly differentiated thyroid cancer cell lines with and without BRAF V600E mutations in vitro." (PMID 17179987, 2007). "On the contrary, thyroid cancer stem cells without BRAF mutation produce anaplastic carcinoma cells and follicular carcinoma cells, since the papillary carcinoma cells that were produced further differentiate immediately into follicular cells." (PMID 17453004, 2007). "In Japan, dabrafenib plus trametinib combination therapy was approved for BRAF V600E-positive solid tumors, including thyroid cancers, in November 2023, and another combination therapy, encorafenib plus binimetinib, was approved for BRAF V600E-positive thyroid cancers in May 2024." (PMID 40844731, 2025). "Another retrospective study of dabrafenib plus trametinib combination therapy in BRAF V600E-positive thyroid cancer reported an objective response rate of 73.1% in 27 patients, and the high response rate in that study may have been due to the high proportion of early-stage cases." (PMID 40844731, 2025). "This research concludes that the presence of the BRAF V600E mutation could be useful in supporting the diagnosis of thyroid cancer, due to its high positive predictive value, since 89% of nodules with BRAF V600E mutation were malignant." (PMID 40748901, 2025). "Therefore, the interactions among ROS, TGF‐β1, and BRAF mutants may play a complex role in the pathogenesis of thyroid cancer." (PMID 40620232, 2025). "In addition, numerous studies have discovered that BRAF mutations, which are common in adult thyroid cancer, are not the predominant molecular event in pediatric thyroid cancer." (PMID 38463235, 2024). "Unfortunately, five single-arm and three uncontrolled retrospective studies on MAPK inhibition of metastatic RAI-resistant thyroid cancer with BRAF, RAS, or no detected driver mutation for RAI re-sensitization do not provide any information regarding TERT mutation analysis." (PMID 38642578, 2024). "Therapeutic approaches that use pharmacological inhibitors targeting tyrosine kinase receptors (TKIs), BRAF V600E, Mitogen-activated kinases, mTOR, anaplastic lymphoma kinase, tropomyosin receptor kinases are proposed to reduce radio- and chemoresistance of thyroid cancer." (PMID 38380364, 2024). "In addition, patients carrying the BRAF mutation are having lower CD8 T cells % (p-value: 4.00e-7) and higher Treg cell % (p-value: 6.64e-12), which is consistent with another study of human thyroid cancer." (PMID 38241355, 2024). "Thus, this is a promising therapeutic strategy for BRAF-mutant thyroid cancers." (PMID 38795180, 2024). "Therefore, the BRAF(V600E) mutation was associated with CTHRC1 expression, and both were correlated with immune cell infiltration including CD4+ T cells, CD8+ T cells, and neutrophils, in colon cancer and thyroid cancer patients." (PMID 39052013, 2024). "In addition, the dabrafenib plus trametinib combination therapy is approved for the treatment of patients with BRAF V600 mutation-positive advanced nonsmall cell lung cancer and showed substantial promise in numerous BRAF-dysregulated solid tumor types, including thyroid cancers." (PMID 39064466, 2024).
thyroid cancer (continued). "Using transgenic mouse models of thyroid cancer, Roelli and colleagues showed that double mutants with Braf V600E and Pik3ca H1047R mutations had paradoxically increased ERK signaling when treated with BRAF inhibitors compared to single mutant mice with Braf V600E mutation alone." (PMID 38275291, 2024). "Further studies showed that NG2 was involved in maintaining the activities of multiple RTKs, such as EGFR, FGFR, HER2, IGF-1R, VEGFR and PDGFR, suggesting that these RTKs and their downstream signaling pathways may contribute to the resistance of BRAF-mutant thyroid cancer cells to BRAF inhibitor." (PMID 38795180, 2024). "Cells harboring the BRAFV600E mutation experience persistent activation of the BRAF kinase, leading to continuous and autonomous stimulation of the MAPK pathway, even in the absence of extracellular ligands, contributing to the pathogenesis of thyroid carcinoma." (PMID 38920735, 2024). "Thus, we attempted to determine whether STAG2 inactivation affected glucose or glutamine metabolism of BRAF-mutant thyroid cancer cells." (PMID 37479689, 2023). "There are some molecular alterations that had never been reported in solid tumors before, including BRAF-PXK fusion, FLNC-BRAF fusion, BRAFN486_T491delinsS, PAX8C147R, PTEND252Rfs∗42, and TERTQ302R, as well as the EIF1AX c.338-2A>T splice site mutation and the KIAA1217-RET fusion in thyroid cancers." (PMID 37744220, 2023). "In addition, given that BRAF-mutant thyroid cancer cells usually showed intrinsic resistance to BRAF kinase inhibitors due to the feedback activation of epidermal growth factor receptor 3 (EGFR3/HER3), thus, we only tested the response of these cells to MEK inhibitor GSK1120212 in the present study." (PMID 37479689, 2023). "In summary, the current study demonstrated that the implementation of UG-FNAB and BRAF p.V600E genetic testing in Qilu Hospital significantly improved the malignancy rate in thyroid surgery, reduced unnecessary surgical treatment, and optimized the initial treatment of thyroid cancer." (PMID 36070149, 2023). "BRAF V600E mutations have been shown to be a sensitive but not specific marker for aggressive thyroid cancers, as they are more likely to be associated with aggressive histopathological features such as capsular invasion, extrathyroidal extension, and nodal metastasis." (PMID 38201541, 2023). "Furthermore, BRAF (rapidly accelerating fibrosarcoma homolog B) and RAS (rat sarcoma) gene mutations associated with impaired immunity activate the PI3K signaling pathway, enhancing cell growth, survival, and angiogenesis in thyroid cancer cells." (PMID 37746910, 2023). "Thus, we speculate that c-Myc may act as a key player in STAG2 inactivation-mediated reprogramming of glutamine metabolism in BRAF-mutant thyroid cancer cells." (PMID 37479689, 2023). "Therefore, it would be relevant to test new drug combinations (BRAFi and LDHAi) in BRAF-mutated tumours, including—but not limiting to—thyroid carcinomas." (PMID 37198319, 2023). "Except for BRAF, HRAS, NRAS and TG, whose involvement in PTC is deeply revealed, for the other commonly mutated genes in all tumor stages, we further assayed the relationship between TCGA data, the RNA expression level of thyroid cancer-derived cell lines and their mutational status." (PMID 35996174, 2022). "Additionally, available tumor DNAs were studied using the mentioned gene panel and the somatic variants found were in agreement with each cancer type, including a splicing variant in PTEN in the lung adenocarcinoma sample, and BRAF p.(V600E) and PIK3CA p.(G1049R) in thyroid cancer samples." (PMID 35227301, 2022). "Because BRAF and NF1/PMS2 have significant mutually exclusive relationship, we speculate that the mechanism of gene mutation leading to the occurrence and development of thyroid cancer may be different between the two groups." (PMID 35865459, 2022).